LINC01409 (long independently transcribed non-coding RNA 1409)
Gene: Long non-coding RNA gene on chromosome 1 (778,739 to 810,066, forward strand). Ensembl gene ENSG00000237491.
Diseases named in the same sentence as LINC01409 in open-access papers:
LINC01409 is named in the same sentence as 1 disease in open-access papers, as found by Europe PMC text mining. Sharing a sentence is not in itself a finding about the gene and the disease.
LINC01409 shares sentences with these, for which no sentence is quoted: tumor (2 papers).